IL10 (interleukin 10)
Diseases named in the same sentence as IL10 in open-access papers (continued):
Sharing a sentence is not in itself a finding about the gene and the disease.
infection (continued). "We hypothesize that the lack of measurable systemic TNF-α and IL-10 in blood plasma in the present experiments might be due to time delayed infection, which made it possible to mobilize the innate immune response to combat to infection." (PMID 31434337, 2019). "Likewise, brain tissues of animals with S. epidermidis-infected catheters had higher levels of IL-10 (P < 0.001), IL-1β (P < 0.001), CCL2 (P < 0.001), and CCL3 (P < 0.001) at day 1 postinfection, demonstrating that the CSF inflammatory milieu mirrors that of the brain tissue during early infection." (PMID 31262978, 2019). "However, although capable of efficiently restricting the fungal growth, mu MT mice did not survive the re-infection with Candida albicans, and this was concurrent with the failure to generate IL-10-producing dendritic cells and regulatory CD4(+)CD25(+) T cells." (PMID 31265468, 2019). "However, IL-10 was not downregulated in BMDMs after Mab infection." (PMID 31835481, 2019). "Notably, the presence of NK cell-derived IL-10 did not improve viral clearance, as NKp46-Cre-Il10fl/fl mice and their control littermates Il10fl/fl had a similar viral burden in their spleens at D5 post-infection." (PMID 31803193, 2019). "This group also suggested that IL-10 production and Treg could be related to impaired gamma interferon (IFN-γ) production and altered development of protective T-cell response by inhibiting T-cell proliferation as seen in the early stage of infection with viruses such as HCV." (PMID 30842948, 2019). "In addition to increased IL-10, patients with gram-positive infections had higher levels of IL-17A and a neutrophil predominance in the CSF when compared to patients with gram-negative shunt infection." (PMID 30626412, 2019). "The TNF-α /IL-10 ratios were not significantly changed regardless of the organ, the bacteria lifestyle and the time point post-inoculation, except in the spleen of mice infected with sessile bacteria where they were significantly lower than in non-infected mice at 24 h time point after infection." (PMID 31583108, 2019). "Therefore, LPC could help macrophages to control infection without excessive inflammatory cytokine production either in the absence or presence of IL-10 production." (PMID 29755479, 2018). "Thus, our data showing expansion of IL-10-producing effector CD4+ and CD8+ cells and Tregs, as well as by DCs, during the course of L. donovani infection could account for defective parasite killing by macrophages at later stages of infection." (PMID 29610255, 2018). "After infection in IFNγR−/− mice, MHV-68 may traffic to the spleen through the circulating blood, resulting in altered leukocyte response and leading to the observed decrease in Th2, B cells, monocyte, and dendritic cells, which was accompanied by decreased IL-10." (PMID 30249047, 2018). "However, and during the late phase of infection, viral IL-10 is driving infected cells toward M2-like polarization, which may limit virus clearance by restricting proinflammatory and CD4 T cell responses at sites of infection." (PMID 29921749, 2018). "Similarly, when peripheral blood mononuclear cells (PBMCs) from adults co-infected with three parasites (filaria, hookworm and Entamoeba histolytica) were stimulated with helminth-specific antigens, they produced higher IL-10 levels compared with PBMCs from adults without the triple infection." (PMID 29970128, 2018). "Also, cytokines such as IL-10 and TGF-β may be related to increased infection." (PMID 30186271, 2018). "Accordingly, IL-4Rα-deficient BMDCs, with reduced IL-12 and increased IL-10 secretion, failed to vaccinate BALB/c animals against acute leishmaniasis, while IL-4-sufficient BMDCs producing increased IL-12 and reduced IL-10 successfully immunized BALB/c mice against infection." (PMID 29176972, 2017).
infection (continued). "This suggests that in the absence of anti-inflammatory cytokines (such as IL-10, IL-13, and IL-4), Th1/Th17 cells proliferate simultaneously and are responsible for parasite elimination, although neutrophil migration, and its role in this situation (3.5 weeks post-infection), was not assessed." (PMID 29163510, 2017). "Furthermore, IFNγ levels in this early phase of infection partially condition the subsequent adaptive immune response by inducing IDO-dependent tolerogenic DCs, which subsequently activate tolerogenic Treg that produce IL-10 and TGFβ, inhibit Th2 cells, and prevent fungal allergy." (PMID 29371571, 2017). "Similar to the expression of IL10 in the spleen, IL10 expression was higher in the NDV IBS002 infected bursa indicating this cytokine may help to control and lower the level of pro-inflammatory cytokines and NO in the bursa of the NDV IBS002 infected chicken compared to NDV AF2240 infection." (PMID 28569155, 2017). "In addition to the cell migration, the infection of microglia with P. gingivalis significantly increased the mRNA expression of proinflammatory mediators, including IL-6, TNF-α, and iNOS, without affecting the mRNA expression of anti-inflammatory mediators, including IL-10, arginase-1 and IL-4." (PMID 28924232, 2017). "Overall, EhLPPG induced the strongest infection-and treatment-specific increases in mRNA encoding protective cytokines (Il-1β, 2.7 ± 0.47 [p = 0.018]; NOS2, 4.9 ± 0.3 [p > 0.0001]); however, it had only a moderate effect on mRNA encoding non-protective cytokines (Il-10, 2.5 ± 1.2 [ns])." (PMID 28842620, 2017). "However, no alteration was detected on the production of IL-10 by these cells also demonstrating in vivo the apparent lack of role of this cytokine in L. amazonensis infection even with the inhibition of A2B receptor at the beginning of the infection." (PMID 28791011, 2017). "This reduction in inflammation was associated with lower IFN-γ and increased IL-4 and IL-10 levels (data not shown), which suggests that WGA-Fc therapy may both result in a more rapid resolution of the infection and diminished sequelae of disease, such as complications of fibrosis." (PMID 28939893, 2017). "In contrast, IOE infection that fails to induce memory-like NK cells or provide a protective recall response to Ehrlichia promoted the production of inflammasome-dependent, pro-inflammatory cytokines, including IL-1α, IL-1β, and IL-18 (data not shown), and the immunosuppressive IL-10." (PMID 27092553, 2016). "Here, we show that a low-dose infection with the intestinally restricted helminth parasite Trichuris muris results in the production of Th1 cell-dependent gamma interferon (IFN-γ) and myeloid cell-derived interleukin-10 (IL-10) in the lung without causing overt airway pathology." (PMID 26644379, 2016). "A significant decrease was found in TNF-α/ IL-10 ratio [which was used as a measure of T helper (h) 1/ Th2 balance (proinflammatory and cellular immunity vs. anti-inflammatory and humoral immunity)], compared to patients without infection in the second sample (P = 0,000)." (PMID 27453748, 2016). "Moreover, we assessed whether IL-27 controls IL-10 production by CD4+ T cells only in the spleen during infection or whether it exerts a dominant role in shaping the nonlymphoid CD4+ IL-10+ T cell response." (PMID 26459508, 2016). "Furthermore, the elevation of serum IL-10 levels raises the question of why IL-10 induction did not occur in all infected cattle and whether IL-10 is the only member of this cytokine family that could influence the outcome of infection with FMD virus." (PMID 26582423, 2015). "Also after infection, these cytokine levels were significantly increased in spleen cell cultures of the TLA-vaccinated compared to the sham-vaccinated mice —at this time point also SMG-vaccinated and infected mice showed increased levels of IL-17 and IL-10 compared to sham-vaccinated controls." (PMID 26010355, 2015).
infection (continued). "Infection at delivery, but not earlier in pregnancy, was associated with significantly higher TLR3-mediated IL-6 and IL-10 responses in the first 3 months of life, and with significantly higher TLR3-/TLR7/8-/TLR9-mediated TNF-α and TLR9-mediated IL-10 responses at 6 or 12 months of age." (PMID 26580401, 2015). "Thus our findings indicate that IL-10-producing B cells are induced very early in infection and may have a role in T cell control of HIV-1 during this phase of the infection, possibly contributing to viral set-point establishment in chronic infection and resulting disease progression." (PMID 24586620, 2014). "Since we did not observe positive correlation between IL-10-producing B cell frequency and viral load in chronic established untreated infection, these opposing roles of IL-10-producing B cell function (preventing immune control versus dampening immune activation) could be at play." (PMID 24586620, 2014). "Although intrinsic ADE has been hypothesized to facilitate IL-10 production, most likely through intracellular signaling of the Fcγ receptor II, the virus-cell interaction is also enhanced extrinsically in the canonical ADE pathway by increasing the infection rate in Fcγ receptor-bearing cells." (PMID 25412261, 2014). "Additionally, IL-10 has been shown to be a key cytokine in the resolution for inflammation following infection, meaning that C. jejuni infection in IL-10−/− mice is ultimately chronic and lethal to the mice, as opposed to the acute, self-limiting infection observed in humans." (PMID 25033044, 2014). "Finally, it is interesting to note that STAT3-dependent cytokines, such as IL-6, IL-10, and IL-21, as well as MyD88-dependent IL-1 have been suggested to play a role in memory CD8+ T cell differentiation and functional maturation following immunization and infection." (PMID 24842874, 2014). "Here, we hypothesize that reduction on liver pathology in IL-10 KO mice could be explained in part by other regulatory components of the immune system such as Treg cells and/or TGF-β1 production or even by the reduction of bacterial load during the course of infection." (PMID 24069337, 2013). "Taken together, non-Treg CD4+ T cells from liver on day 7 of infection might be under the control of two different pathways: one that is iNOS/IL-10-dependent, to control resident and activated CD4+ T cells, and a second that is Treg-dependent, to control the newcomer CD4+ T cells." (PMID 24312297, 2013). "However, with ANDV infection, neither Il5 or Il10 expression appear elevated." (PMID 23570545, 2013). "Furthermore, IL-10 blocking antibodies or genetic IL-10-deficiency did not prevent T cell exhaustion and viral clearance in response to LCMV-DOC, in contrast to LCMV clone 13 infection." (PMID 23696736, 2013). "Therefore, infection of DCs with B. abortus S19 does not inhibit but modifies the maturation-induced secretion of cytokines, i.e., it significantly enhances the secretion of IL-12p70 and IL-10." (PMID 23805193, 2013). "Similarly, in experimental models the protective response to infection with Toxoplasma gondii is associated with the production of IFN-γ; however, in the absence of IL-10, infected animals succumb earlier as a result of uncontrolled immunopathology, although parasite control seems to be intact." (PMID 23824716, 2013). "To explore the effect of DC-mediated protection on the early secretion of IL-10 by antigen-specific T cells, we compared the cytokine activity of cells in the lymph nodes draining the lesions of vaccinated versus non-vaccinated mice at different time points after infection with L. major." (PMID 23825956, 2013). "In addition, blood samples were collected at 2, 6, 24 and 48 h post-infection to analyse the production of inflammatory cytokines such as TNF-α, IFN-γ, IL-6, keratinocyte chemoattractant (KC or CXCL-1, equivalent to human IL-8) and anti-inflammatory cytokine IL-10." (PMID 24107297, 2013).
infection (continued). "In addition, we demonstrate that IL-10 inhibits HIV-1 replication in HCs and propose that the high basal production of IL-10 in HCs, similar to regulatory macrophages, plays a central role in limiting their ability to replicate HIV-1 after initial infection, which may offset vertical transmission." (PMID 23217137, 2012). "However, it is also noteworthy that the immune-modulatory cytokine IL10 is induced upon infection by MCMV in MΦs and in vivo and since IL10 is known to function as an anti-inflammatory mediator, it is possible that a host IL10 autocrine loop might be involved in modulating TNFα." (PMID 22952450, 2012). "Therefore, further studies are necessary to delineate IL-10+ cells within the NK1.1− TCRβ− population and the TCRβ+ population, as these may also contribute to the regulation of inflammation in the liver during infection." (PMID 22880122, 2012). "Interestingly, for TNF-αactivation was largely independent of productive infection, a finding that also indicates that induction of IL-6 and IL-10 are not being induced as a by-product of TNF-α up-regulation, but rather that these mediators are independently induced." (PMID 21572983, 2011). "Also, IL-10 and TGF-β were expressed similarly in the lesions throughout the critical points of infection, thus discarding the possibility of any strong interference of differential Treg activity in the lesion site could be determinant for the disease outcomes." (PMID 21390155, 2011). "Finally, they represented diverse molecular classes – cytokines (TNF, IL-12p40, IL-6, IL-10, GM-CSF), chemokines (RANTES, MCP-1), enzymes (iNOS, cyclooxygenase [COX] 2) and cell-surface co-stimulatory proteins (Delta-4, CD40, GITRL) – with known roles in immune responses to infection." (PMID 21170273, 2010). "The enhanced and early production of CXCL10 that we observe in Mtb-infected IL-10−/− mice may contribute to the increased number of IFN-γ-producing CD4+ T cells recruited to the lungs, in keeping with the known role of CXCL10 in Th1 migration during other infections." (PMID 20518032, 2010). "However, the down-regulation exerted on the iNOS by IL-10 and other anti-inflammatory cytokines is not sufficient to explain the decreased NO production observed in the blood at the neurological stage of the infection." (PMID 20169057, 2010). "We propose that IL-10-producing Th1 cells may be the essential regulators of acute infection-induced inflammation and that such “self-regulating” Th1 cells may be essential for the infection to be cleared without inducing immune-mediated pathology." (PMID 19343213, 2009). "Furthermore, CD4+ T cells (and potentially B cells) may be the major source of IL-10 during infection since plasma IL-10 does not increase above baseline levels in RAG−/− mice except on day 3 pi of PyL infection." (PMID 18401464, 2008). "In this context, the present study aims to compare IL-10, IL-2, IL-6, IL-8, and TNF-α levels between patients with and without HAdV-36 infection." (PMID 40284995, 2025). "Mechanistically, DC production of IL-10 is triggered through TLR4 signaling via ERK phosphorylation and NF-κB activation, and interestingly, this does not require infection but depends on parasite-DC contact." (PMID 41568009, 2025). "In sera of WT mice, IL-20RA cytokines, but not IL-10, IL-12, or IFN-γ, were detected in mock-infected animals, and EV-A71 infection significantly increased IL-19 and slightly increased IL-20 levels." (PMID 41550952, 2025). "In control mice prior to infection, IL10+ B cells showed higher levels of CD73 and CD39 mRNA, and their corresponding cell surface proteins, compared to IL10 negative B cells." (PMID 41191641, 2025). "IL-4, IL-10, and TNF remained below the detection limit in all experimental groups, regardless of infection status (data not shown)." (PMID 41415569, 2025). "IL-4, IL-10, and TNF-α levels were below the detection limit in all experimental conditions, regardless of infection status (data not shown)." (PMID 41415569, 2025).
infection (continued). "Serum levels of IL-10, IL-2, IL-6, IL-8, and TNF-α were analyzed and compared between patients with and without HAdV-36 infection." (PMID 40284995, 2025). "Analgesic treatment did not alter the internal cytokine levels, including IFN-γ, IL-10, IL-1β, and TNF-α, at 24 hours after infection." (PMID 39281680, 2024). "Increased levels of il-17, as well as il-10 in the absence of OPN both in vitro and in vivo, seem to be under the control of infection by the parasites and correlate with the post-infection acceleration of T1D." (PMID 39436890, 2024). "Another remark is that suppression of IL-10 and TGF-β1 production upon FeAdV infection was not tested in PCa ongjos cells." (PMID 39682467, 2024). "During PDTB, the Th profile was predominantly mono-cytokine and polyfunctional, with populations of IL-4+ or IL-10+ cells most abundant, consistent with their increase during PDTB irrespective of infection." (PMID 37898618, 2023). "Studies in these infection models showed that when Bhlhe40 is absent in CD4+ T cells, IL-10 production increases, while IFN-γ production decreases." (PMID 37843306, 2023). "Among the genes for T cell-mediated factors, the expression of genes for regulatory molecules such as IL-10 and IL-22 was increased by SCFA and infection, but that for other inflammatory molecules was not." (PMID 37865711, 2023). "Despite that, IL-4 and IL-10 knockout mice have impaired IL12 production and Th1 response and are not able to resolve infection by L. amazonensis or L. major." (PMID 37000792, 2023). "At 4 weeks post infection both groups produced increased levels of IFN-γ, IL-4, IL-10, and TNF-α from splenic cells that were not statistically different between the groups, however, the trend was for higher mean levels in the WT-inoculated animals." (PMID 37185599, 2023). "Infection with S. mansoni had no impact on H1-specific or anti-CD3-induced production of IFNγ, IL-17, and of IL-10 from draining inguinal lymph nodes." (PMID 36753434, 2023). "Additionally, the frequency of IL-10+ CD4+ T cells correlated with protection against symptomatic infection and induction of asymptomatic infection, consistent with the hypothesis that Tr1 cells can protect against excessive pathology during infection and may contribute to clinical immunity." (PMID 36389662, 2022). "The frequency of intracellular IL-10 expressing CD8+ suppressive T cells was higher in CHB carriers (0.09%) than in HBV non-infected individuals (0.055%), resolved infections (0.06%), or OBI carriers (0.07%) (P < 0.05)." (PMID 35464946, 2022). "Increased HGF has been found in plasma during infection in both septic and nonseptic patients, where early phase septic patients displayed elevated levels of TNF and IL‐10,24 signifying an active inflammatory response." (PMID 35285058, 2022). "In the absence of ICOOH, challenge infection (NC group) with E. maxima increased the gene expression of IFN-γ (p < 0.001, 1.2 × 10−4 to 4.5 × 10−3) and IL-10 (p = 0.012, 3.2 × 10−4 to 1.8 × 10−3) in the distal jejunum compared to that of the CON group." (PMID 35812452, 2022). "Our results revealed that IL-10, IL-8, IL-6, IFN-, IL-17A, and IL-17F levels in patients with bacterial lung illness were abnormally higher than those without infection." (PMID 36319826, 2022). "Instead, infection with the virulent 22653/14 ASFV did not alter any surface marker expression and did not trigger the release of either IFNβ, anti-inflammatory IL-10, proinflammatory (IL-1β, IL-6, IL-8, TNF-α), and pro-Th1 (IL-12, IL-18) cytokines." (PMID 35215216, 2022). "Lymphocytes isolated from the brains, but not the CLNs, of IL10-/- mice had lower numbers and percentages of GARP+ cells 3 and 5 days after infection than WT mice." (PMID 36016413, 2022). "Here we found that increased plasma concentrations of IL-10, MCP-1, IL-1rα, IL-2, IL-6 and SCGFβ had a negative impact on CD4:CD8 ratio during acute infection (< 180 days post infection), as evaluated by linear regression model." (PMID 35165387, 2022).